MSN (moesin)
Description:
Ezrin-radixin-moesin (ERM) family protein that connects the actin cytoskeleton to the plasma membrane and thereby regulates the structure and function of specific domains of the cell cortex. Tethers actin filaments by oscillating between a resting and an activated state providing transient interactions between moesin and the actin cytoskeleton. Once phosphorylated on its C-terminal threonine, moesin is activated leading to interaction with F-actin and cytoskeletal rearrangement. These rearrangements regulate many cellular processes, including cell shape determination, membrane transport, and signal transduction. The role of moesin is particularly important in immunity acting on both T and B-cells homeostasis and self-tolerance, regulating lymphocyte egress from lymphoid organs. Modulates phagolysosomal biogenesis in macrophages (By similarity). Also participates in immunologic synapse formation.
Synonyms: HEL70; IMD50
Tractability: Small molecule: a structure with a bound ligand is known. Antibody: UniProt places it where antibodies can reach, with high confidence; its Gene Ontology location is reachable by antibodies, with high confidence; the Human Protein Atlas places it where antibodies can reach. PROTAC: ubiquitination databases record sites on it; its protein half-life has been measured; a small molecule that binds it is known.
Gene: Protein-coding gene on chromosome X (65,588,377 to 65,741,936, forward strand). Ensembl gene ENSG00000147065.
Subcellular location: Cell membrane; Cytoplasm, cytoskeleton; Apical cell membrane; Cell projection, microvillus membrane; Cell projection, microvillus
Subcellular location (Human Protein Atlas): Plasma membrane
Pathways (Reactome):
Sensory Perception: Sensory processing of sound by inner hair cells of the cochlea; Sensory processing of sound by outer hair cells of the cochlea
Developmental Biology: Recycling pathway of L1
Disease: Signaling by ALK fusions and activated point mutants
Immune System: Gene and protein expression by JAK-STAT signaling after Interleukin-12 stimulation
Gene Ontology:
Molecular function: cell adhesion molecule binding; double-stranded RNA binding; enzyme binding; protein binding; protein kinase binding; signaling receptor binding; actin binding; structural constituent of cytoskeleton; cytoskeletal protein binding
Biological process: establishment of endothelial barrier; establishment of epithelial cell apical/basal polarity; gland morphogenesis; immunological synapse formation; leukocyte cell-cell adhesion; leukocyte migration; membrane to membrane docking; positive regulation of early endosome to late endosome transport; positive regulation of gene expression; positive regulation of protein catabolic process; positive regulation of protein localization to early endosome; regulation of cell shape; regulation of cell size; regulation of lymphocyte migration; regulation of organelle assembly; T cell aggregation; T cell migration; T cell proliferation; cytoskeleton organization
Cellular component: apical part of cell; apical plasma membrane; blood microparticle; cell periphery; cell surface; cytoplasm; extracellular exosome; extracellular region; filopodium; focal adhesion; microvillus; nucleus; perinuclear region of cytoplasm; plasma membrane; pseudopodium; vesicle; adherens junction; cytoskeleton; cytosol; basolateral plasma membrane; microvillus membrane; uropod
Gene-disease validity (ClinGen):
ClinGen rates the evidence that MSN causes each of these diseases.
combined immunodeficiency due to moesin deficiency (X-linked): Definitive.
Homologues: Orthologues: chimpanzee MSN (100% identical), macaque MSN (100% identical), guinea pig MSN (99% identical), pig MSN (99% identical), mouse Msn (99% identical), dog MSN (98% identical), rat Msn (93% identical), tropical clawed frog msn (89% identical), Drosophila melanogaster Moe (60% identical). Paralogues in human: RDX (81% identical), EZR (74% identical), NF2 (45% identical), FRMD4A (26% identical), FRMD4B (26% identical), ERMN (13% identical).
Diseases named in the same sentence as MSN in open-access papers:
MSN is named in the same sentence as 172 diseases in open-access papers, as found by Europe PMC text mining. Sharing a sentence is not in itself a finding about the gene and the disease. The quoted sentences say what the papers report.
breast carcinoma (62 papers, 2008 to 2025). "In some malignant tumors such as gastric adenocarcinoma, breast cancer, and melanoma, upregulated moesin expression was found associated with high histological grade and advanced stage of the tumor and indicated poor prognosis." (PMID 38267973, 2024). "Studies in breast cancer indicate that aberrant activation of Moesin causes over-stabilization of the actin cytoskeleton, which mediates EMT and metastasis." (PMID 36879821, 2023). "Our study, for the first time, reveals the underlying molecular mechanism of overexpression of Moesin in breast cancer." (PMID 37736741, 2023). "A plethora of reports suggests that Moesin is overexpressed or aberrantly activated in diverse cancer types, including breast cancer, which is significantly associated with poor survival of cancer patients." (PMID 37736741, 2023). "Our in vitro and in vivo studies reveal that FBXW2 prevents breast cancer progression by promoting Lys-48-linked polyubiquitination to direct proteasomal degradation of Moesin through the canonical SCF complex." (PMID 37736741, 2023). "In the search for the signaling pathways through which ERα leads to moesin activation in breast cancer cells, we used different pharmacological inhibitors linked to ERα or moesin to treat estrogen-receptor positive breast cancer cells." (PMID 18493596, 2008). "Previous studies have shown that basal-type and post-EMT breast cancer cell lines are particularly sensitive to dasatinib, with elevated expression of genes such as moesin (MSN), caveolin-1 (CAV1), and yes-associated protein-1 (YAP1), which are associated with the SRC signaling pathway." (PMID 41462902, 2025). "Estrogen administration to breast cancer cells is associated with ERα membrane translocation and with the rapid formation of such specialized cell membrane structures through the activation of the actin-binding protein, moesin." (PMID 24904530, 2014). "MSN was significantly overexpressed in ADR-resistant breast cancer cells, MDA-MB-231/ADRr and MCF7/ADRr, compared to other drug-resistant cell lines." (PMID 40696387, 2025). "Following this confirmation, we investigated the role of MSN in breast cancer by establishing cell lines with altered MSN expression in TNBC." (PMID 40696387, 2025). "In breast cancer, it has been observed that in vitro, the phosphorylation of moesin by ROCK can stabilize the levels of PD-L1." (PMID 39507618, 2024). "Moesin is upregulated in various human cancers, including breast cancer, prostate cancer, pancreatic cancer, lung cancer, and melanoma." (PMID 39445005, 2024). "In HER2-positive breast cancers, moesin expression decreased, which correlated with increased HER2 expression." (PMID 39457653, 2024). "The same phenomenon was observed in rhabdomyosarcoma and breast cancer where silencing of ERM proteins suppressed tumor growth, and high MSN expression was associated with increased proliferation, migration, and invasion of glioblastoma cells." (PMID 37446127, 2023). "We showed that FBXW2 suppresses breast cancer progression through directing proteasomal degradation of Moesin." (PMID 37736741, 2023). "Overall, our study established tumor suppressor FBXW2 as a bonafide E3 ligase for Moesin in breast cancer." (PMID 37736741, 2023). "Immunoblotting results showed that Moesin expression is higher in luminal and highest in TNBC cells compared to normal cells, suggesting that Moesin is highly expressed in 50% breast cancer cell lines tested." (PMID 37736741, 2023). "Taken together, FBXW2 directly interacts with Moesin and shows an inverse correlation with Moesin’s expression in breast cancer cell lines and patient samples." (PMID 37736741, 2023). "Further, FBXW2 is under expressed whereas Moesin is highly upregulated in breast cancer cell lines and patient samples and their converse correlation is closely associated with poor patient prognosis." (PMID 37736741, 2023).
breast carcinoma (continued). "Further, Moesin functions as a critical oncogene in breast cancer to drive growth, proliferation, invasion, and metastasis." (PMID 37736741, 2023). "We showed that FBXW2 acts as a negative regulator of Moesin at the posttranslational level and it is under expressed in breast cancer cell lines and patient samples." (PMID 37736741, 2023). "The expression of MSN is correlated with the histological grade, development, and recurrence of breast cancer." (PMID 37446127, 2023). "Moesin functions as a potential oncogene in breast cancer by promoting cancer initiation, progression, and metastasis." (PMID 37736741, 2023). "Collectively, FBXW2 suppresses breast cancer progression both in vitro and in vivo by negatively regulating Moesin." (PMID 37736741, 2023). "We selected Moesin for further study because of its potential oncogenic activity in different cancers, including breast cancer." (PMID 37736741, 2023). "Taken together, these results show that FBXW2 controls the proliferation of breast cancer cells through controlling Moesin expression." (PMID 37736741, 2023). "Next, we examined the expression levels of FBXW2 and Moesin in normal breast epithelial cell line and different subtypes of breast cancer cell lines (luminal, human epidermal growth factor receptor 2 positive (HER2+), and triple negative breast cancer (TNBC))." (PMID 37736741, 2023). "This study presents the tumor-suppressive action of AMPK-inhibited PBMC/lymphocyte-derived CM and evaluates the role of ENO1/MSN-Mtdh regulatory axis as well as PABPC1 in suppressing the progression of breast cancer." (PMID 36923539, 2023). "So, these results showed that FBXW2 inhibits malignancy of breast cancer cells in vitro by negatively regulating Moesin." (PMID 37736741, 2023). "In line with this, ROCK-mediated moesin phosphorylation regulated the PD-L1 stability by preventing its degradation in breast cancer cells." (PMID 35159327, 2022). "For example, adipokines such as LEP and RETN promote metastasis through activation of ezrin, radixin and moesin proteins in breast cancer cells." (PMID 36362348, 2022). "They investigated the activation of ROCK1 gene by RhoA increased TMEM16A channel activity owing to the phosphorylation of moesin at T558 in breast cancer cells." (PMID 35668455, 2022). "With clinical application value, moesin silencing restores the sensitivity to Doxorubicin of breast cancer cells." (PMID 33838692, 2021). "In fact, moesin has been found to be significantly upregulated in breast cancer, prostate cancer, pancreatic cancer, and other cancers, but there were few reports on changes the upregulation will cause in cancer." (PMID 33838692, 2021). "During EMT, actin filament remodeling depends on the increased expression of the ERM protein moesin; moesin, as an EMT marker, supports the association of moesin, Snail, and EMT and thereby affects the prognosis of breast cancer." (PMID 33833821, 2021). "We identified a juxtamembrane positively charged cluster responsible for the interaction of MT1-MMP with ERM (ezrin/radixin/moesin) cytoskeletal connectors in breast carcinoma cells." (PMID 32028690, 2020). "The expression of CD44, CD44 cross-linking and Moesin phosphorylation in breast cancer cells was assessed by Western Blot assays." (PMID 33292278, 2020). "Increased moesin expression is related to invasion and metastasis and is also correlated to a progressive pathological state of pancreatic and breast cancer." (PMID 32098295, 2020). "Further, we found that knocking down MSN in two breast cancer cell lines (MDA‐MB‐231 and BT‐549) reduced the PD‐L1 level." (PMID 32941674, 2020). "For instance, ezrin inhibition reduced metastatic spread of OS and breast cancer, while silencing moesin and radixin were shown to reduce migration and invasion of melanoma and colon cancer, respectively." (PMID 33005093, 2020). "In this regard, moesin is an adverse prognostic marker for several tumours, including breast cancer." (PMID 32028690, 2020).
breast carcinoma (continued). "Moesin phosphorylation was inhibited by CD44 de-crosslinking in breast cancer cells and Moesin shRNA knockdown attenuated the promotion of CD44 cross-linking on cell migration and invasion." (PMID 33292278, 2020). "Analysis of transcriptome data sets from TCGA (The cancer genome atlas) using Oncomine and cBioPortal, confirmed the inverse correlation between BRCA1 and CCL5/ Moesin in breast cancer." (PMID 30224826, 2018). "Through the modulation of Moesin, androgens alter the architecture of cytoskeleton in T47D breast cancer cell and promote cell migration and invasion." (PMID 27746764, 2016). "Through the modulation of the actin-binding protein, Moesin, androgens alter the architecture of the cytoskeleton in T47D breast cancer cells and promote cell migration and invasion." (PMID 27746764, 2016). "Our previous studies in EVs shed from multidrug resistant breast cancer cells showed a selective packaging of Ezrin, Radixin, Moesin and CD44 in resistant breast cancer cell-derived EVs." (PMID 26938523, 2016). "This is consistent with our previous reports where steroid hormone receptors activate G-protein–ROCK-2-Moesin signaling in breast cancer and other cell models." (PMID 27746764, 2016). "Moesin activation in breast cancer cells is the main established mediator of the estrogen-induced formation of pseudopodia and ruffles." (PMID 24904530, 2014). "Since Thr558-moesin phosphorylation in breast cancer cells is triggered exclusively by ERα, we silenced the expression of ERβ in T47-D cells with an siRNA system." (PMID 24904530, 2014). "In this paper, we studied the effects of estetrol on migration and invasion of ER+ breast cancer cells and we related these observations to actin remodeling and to the activation of moesin, characterizing the signaling steps involved in these actions." (PMID 24904530, 2014). "Specifically, we looked into possible regulatory actions of E4 on the actin regulatory molecule, moesin, which is responsible in breast cancer cells for actin re-shaping during cell movement." (PMID 24904530, 2014). "In conclusion, our findings manifest that progesterone and MPA promote breast cancer cell movement via rapid actin cytoskeleton remodeling, which are mediated by moesin activation." (PMID 18665217, 2008). "Our previous findings show indicate that sex steroid receptors, such as the estrogen receptor alpha, control moesin activity in vascular cells as well as in breast cancer cells." (PMID 18665217, 2008). "To test the impact of the ER-dependent signaling to moesin on breast cancer cell invasion we performed three-dimensional invasion assays using matrigel." (PMID 18493596, 2008). "We also find that human breast cancers display a deranged over-expression and over-activation of moesin respect to normal breast tissues and/or benign fibroadenomas." (PMID 18493596, 2008). "In this paper, we discover that PR signals to moesin in breast cancer cells and this leads to rapid actin emodeling that supports horizontal cell movement and invasion of three-dimensional matrices." (PMID 18665217, 2008). "In this paper we study the effects of estradiol on the migration and invasion of ER+ or ER− breast cancer cells and we relate these observations to actin remodeling and to the activation of moesin, characterizing the signaling steps involved in these actions." (PMID 18493596, 2008). "These signaling intermediates, including moesin, are all required for actin remodeling as well as breast cancer cell migration and invasion." (PMID 18493596, 2008). "We here show that estrogen enhances horizontal migration and invasion of three-dimensional matrices of ER+ breast cancer cells by recruiting the actin-binding protein, moesin." (PMID 18493596, 2008). "Moesin expression was significantly reduced when T47-D breast cancer cells were transfected with antisense moesin PONs for 72 h." (PMID 18493596, 2008).